IL2RA (interleukin 2 receptor subunit alpha)
Diseases named in the same sentence as IL2RA in open-access papers (continued):
Sharing a sentence is not in itself a finding about the gene and the disease.
skin cutaneous melanoma (1 paper, 2016). "The Treg transcription factor FOXP3 was significantly lower (p < 0.01), while CD25 (IL2RA) was significantly higher (p < 0.0001) in PDAC (n = 147) than in skin cutaneous melanoma (n = 472) indicating that CD25 is expressed in PDAC by non-regulatory T cells as well." (PMID 27762323, 2016).
vasculitis (1 paper, 2014). "Associations of polymorphic variants in the IL2RA gene which encodes CD25 with vasculitis further support this possibility." (PMID 25056155, 2014).
vitamin D deficiency (1 paper, 2021). A nutritional condition produced by a deficiency of VITAMIN D in the diet, insufficient production of vitamin D in the skin, inadequate absorption of vitamin D from the diet, or abnormal conversion of vitamin D to its bioactive metabolites. "It is believed that environmental (e.g., virus infections, vitamin D deficiency, smoking and obesity) and genetic (e.g., human leukocyte antigen (HLA) genes, and, among many other genes the IL2RA gene) factors may activate immune-mediated processes which play a major role in the pathogenesis of MS." (PMID 35005590, 2021).
tumor (171 papers, 1987 to 2026). "We conducted an analysis on the expression levels of the TERT and IL2RA genes in tumor microenvironment-associated cells within OS, using the TISCH database." (PMID 38431660, 2024). "IGLL5 and IL2RA expression were also positively associated with the stage of ccRCC patients, including high tumor stage, tumor grade, T stage, and more lymph node metastases (p < 0.05)." (PMID 34888353, 2021). "Our result showed that higher purine metabolism in tumor epithelial cells is strongly associated with markers of Treg activation (CCR8, FOXP3, and IL2RA) and levels of ADORA2A, encoding the well-known purine receptor A2AR, in Tregs." (PMID 39252976, 2024). "Studies have also shown that overexpressing IL2RA in specific tumor microenvironments can markedly improve anti-tumor activity by promoting T-cell proliferation and persistence." (PMID 39439803, 2024). "Strategic modulation of IL2RA expression in TCR-T therapies can significantly enhance treatment efficacy by increasing T-cell sensitivity to IL-2 within the tumor microenvironment." (PMID 39439803, 2024). "The selection of cytokines was based on their significant role in regulating the tumor microenvironment, including promoting either the Th1 (IL-2RA, IL-12(p40), IL-15, TNF-α, IL-1β, IL-1RA, and IFN-γ) or the Th2 (IL-4, IL-6, IL-8, and IL-10) profile." (PMID 39768997, 2024). "By contrast, these tumours lack the typical markers for GATA3+ PTCL‐NOS such as Il2ra, il9r, and Gata3 itself." (PMID 35895495, 2022). "KEGG pathway analysis revealed IL2RA in pathways such as immune cell activation and tumor microenvironment regulation." (PMID 36120307, 2022). "MicroCellClust identifies a cluster of 23 cells originating from the tumor, characterized by the expression of Treg associated genes such as FOXP3 and IL2RA." (PMID 33830183, 2021). "We found significant associations between tumor mRNA expression of IL2RB and NOTCH1 genes and gender and between tumor mRNA expression of IL2RA and MAP2K1 genes and age." (PMID 33672900, 2021). "CD4+LAIR2+ cells highly expressed Treg cell lineage markers, including IL2RA, CTLA4, TNFRSF18, ICOS, TIGIT, and tumor-associated Treg cell marker CCR8, consistent with CD4+ LAIR2+ cells being of Treg lineage and not recently activated T cells." (PMID 35008369, 2021). "For ccRCC, IHC images indicated that normal renal tissue had weak staining for IGLL5 and IL2RA, but relatively strong staining patterns for IGLL5 and IL2RA were observed in the cytoplasm of tumor tissues." (PMID 34888353, 2021). "The HATMSC2-MVs used in this study affect both histologically different cell lines, the ES-2 cells and the OAW-42 cells, by increasing the production of tumor-suppressive cytokines, such as IL-1ra, IL-2, IL-2Ra, IL-12-p40, IL12-p70, IL-15, and IFN-γ." (PMID 33266317, 2020). "Gene-gene interactions were detected in the relapse group; CCL5, GZMB, IL2RA, SELE, and CCL8 interacted with CCR5 in both the pCR and relapse groups and were associated with tumour progression, and metastasis." (PMID 33138797, 2020). "IL2RA is extensively involved in T cell regulation and plays a crucial role in tumor immunotherapy." (PMID 37285836, 2023). "Gene expression analysis of the tumor lesions for selected immune-related genes, confirmed a clear induction of markers associated with T cell activation and recruitment in SD101-treated mice (Perforin, Icos, Cd38, Ifng, Il2ra, Il7 and Cxcl10)." (PMID 37365634, 2023). "And for the clinical relevance of IL2RA expression patterns, there was of significant difference in clinical grade, indicating that PRF1 and IL2RA might be involved in the mechanism of tumor progress." (PMID 36097539, 2022). "Notably, we did not observe the direct association of TET3 with these factors, and found that several tumor suppressor genes (CDKN2B, ZIC2, and miR-196a) and oncogenes (PAX2, IL2RA, SOX11, and PAK7) were associated with TET3 in AML biology." (PMID 32209730, 2020).
tumor (continued). "Finally, IL2RA is an Interleukin 2 receptor subunit alpha protein involved in suppressing the activity of the immune system against tumor cells." (PMID 32272578, 2020). "CD36 also demonstrated positive correlations with immune checkpoint molecules, including C10orf54, EDNRB, TLR4, ENTPD1, IL10, and IL2RA, suggesting that it may contribute to immune escape mechanisms by engaging checkpoint pathways in the tumor microenvironment." (PMID 41550652, 2025). "In addition, stratified analysis showed that PRF1 and IL2RA might be involved in the mechanism of tumor progress." (PMID 36097539, 2022). "According to these findings, IL2RA may play a variety of roles in tumor immune response." (PMID 34796785, 2021). "DUSP4 is implicated in the development of T cell exhaustion, and we also identified overexpression of several other classically defined exhaustion marker genes such as ENTPD1, IL2RA, and CXCR6, consistent with an immune-exhausted tumor microenvironment." (PMID 40848148, 2025). "We examined cytokine secretion profiles (IL-2, IL-4, IL-6, and IFNG) from activated T cells (CD69, IL-2RA, CD38, and HLA-DRB1) to evaluate T-cell activation in the CM tumor microenvironment, revealing consistently low expression levels." (PMID 40959090, 2025). "The results showed a significant correlation between CHST11 and certain tumor immunostimulators (CD28, IL2RA, and TNFSF13B), tumor immunoinhibitors (CD96 and LGALS9), and MHC proteins (HLA-DRA and HLA-DMB)." (PMID 38565604, 2024). "The results showed that IL2RA, DNMT3B, ADRM1, and NRIP1 were highly expressed in tumor tissue compared to normal tissue, while ALDH2, NYNRIN, LSP1, and CALCRL were the opposite." (PMID 38322112, 2024). "This strategy is supported by in vitro evidence showing improved T-cell function following IL2RA upregulation, suggesting that future clinical trials should explore this approach to enhance TCR-T therapies in hostile tumor microenvironments." (PMID 39439803, 2024). "Among these, IL2RA and TNFRSF9 have been previously established as functional markers for tumor-infiltrating Treg." (PMID 38887516, 2024). "Regulatory T cells (Tregs), CD4+IL2RA+FOXP3+, were found mixed with CD4 T cells from tumor samples (tCD4)." (PMID 39516494, 2024). "IL2RA-specific TCR-T cells effectively induced tumor cell apoptosis in in vitro experiments and demonstrated strong tumor suppression in in vivo studies." (PMID 39439803, 2024). "While comparing with normal Tregs, tumor Tregs had increased expression of multiple genes related with immune suppression, including DUSP4, IL2RA, TNFRSF4, LAYN and LGALS1." (PMID 35664061, 2022). "In our study, LTA was positively correlated with CD8+ T-cell infiltration and its markers’ expression after adjusting by tumor purity, such as CD8A, CD8B, and IL2RA." (PMID 35155447, 2021). "At the cellular level, USP18, TLR7, IL21R, GCNT1 and CHST7 were expressed in various tumor cell lines, while the expression of LHX2, IL2RA and IL5RA was low in CCLE." (PMID 34001679, 2021). "Both CD4_5 and CD4_7 had expression of regulatory T (Tregs) cell markers, with higher levels of FOXP3, IL2RA (CD25), CTLA4, and TNFRSF18 (GITR) in the tumor-predominant CD4_5." (PMID 33504936, 2021). "Most Treg cells were expressed in tumor patients, including TreC1 (FOXP3-IL2RA+) and TreC2 (FOXP3+IL2RA+)." (PMID 34745098, 2021). "The GEPIA results showed that the mRNA expression levels of USP18, IL2RA and IL21R were higher in tumor samples than in normal samples." (PMID 34001679, 2021). "A high level of IL2, IL2RA, and IL2RB gene expression and their relationships with tumor progression and malignancy have been previously reported." (PMID 33672900, 2021). "The C4 subset was annotated as Treg cells based on the high expression signature genes of tumor-infiltrating Tregs (FOXP3, IL2RA, IL2RB, IL2RG, IL10RA, MAGEH1, LAYN, and GATA3)." (PMID 34663810, 2021).
tumor (continued). "Consistently, RNAseq analysis of human cancers revealed a strong positive correlation between the expression of Treg markers (FOXP3, IL2RA) and myeloid cell markers (MRC1, CD14, and ITGAM) across several tumor types." (PMID 32782249, 2020). "In HCC, we observed increased expression of several more activation- (IFNG, CD38, IL2RA, TNFRSF9) and exhaustion-related (TIGIT, CTLA4, PDCD1, ENTPD1) genes in tumor MAIT cells." (PMID 32849590, 2020). "Lastly, in order to make the newly obtained knowledge easily accessible to experimental immunologists, we showed the expression of NFAT5, IL2RA, CCR8, BCL6, and KCNK5 in the tumor-infiltrating T cells in a flow cytometric format." (PMID 30061879, 2018). "KCNN4 has been shown to have positive correlations with several costimulatory molecules (CD276, CD40, CD70, CD80, CD86), immune signaling receptors (IL2RA, MICB, NT5E), and multiple TNFRSF family members, suggesting its involvement in immune modulation, inflammation, and tumor‐immune interactions." (PMID 40952239, 2025). "The expression of activation-specific genes (IFNG, GZMB, and TNFRSF9) and cell proliferation-specific genes (IL2, IL2RA, and CD28) decreased with the increasing rounds of tumor stimulation, especially from round 2 (the round in which tumor-killing ability begins to decline)." (PMID 39657666, 2024). "Thus, considering the counterintuitive association of IL2RA+ VSIG4 + ATAMs infiltration with favorable prognosis, if immunosuppressive molecules could be specifically targeted in this population, it could skew their phenotype to an M1, further helping eliminate the tumor." (PMID 38022609, 2023). "Thus, the presence of IL2RA+ VSIG4 + ATAMs correlates with high lymphocyte infiltration (B, CD8+, and Tregs) as well as BRAF and Ras signaling in the tumor." (PMID 38022609, 2023). "After stimulation, the percentage of C02-Activated-IFNG and C06-Activated-IL2RA of TCR-TMART-1 was downregulated, while the fragment of C01-Activated-CD69, C11-Activated-IL15, and C12-Cytotoxic-GNLY was upregulated with increased tumor PD-L1 levels." (PMID 33754038, 2021). "Notably, LINC01857 and LINC02446 were the shared competing lncRNA of both IL2RA and IL7R, supportive of their significant involvement in tumor progression." (PMID 34159752, 2021). "Therefore, we analyzed the levels of expression of IL-2, IL-2RA and CD27 together with CD40LG and the anti-apoptotic regulator BCL2L1 on CD8+ TILs isolated from peripheral blood and tumor tissues of Bhi OPSCC patients (n = 4; Cohort 3)." (PMID 31623665, 2019). "In addition, unlike CD4 and CD8 cells, which are infiltrating tumor cells, IL2Ra-positive cells are mainly located within and around areas of necrosis, which is expected of regulatory cells." (PMID 39769460, 2024). "Stimulation by BiTE promotes the expression of CD69 and IL2RA, known as T-cell activation markers, on the vast majority of CD8 and CD4 T-cells, thus allowing all CD8 and CD4 T-cell subpopulations except the naive T cells to be involved in redirected tumor cell lysis." (PMID 38672662, 2024). "In addition, we revealed that LINC01857, LINC02446, and LINC02384, as competing endogenous RNAs (ceRNAs) of IL2RA and IL7R, were oncogenes, while miR‐203b‐3p and miR‐891a‐5p, as microRNA sponges of IL2RA and IL7R, respectively, act as potential tumor suppressor molecules." (PMID 34159752, 2021). "The OS T-reg cells expressed the canonical gene signature including the FOXP3 and IL2RA, and they also showed relatively high immune-inhibitory molecules including the CTLA4 and TIGIT, which may contribute to T-reg cell-mediated suppression of anti‐tumor immune responses in OS lesions." (PMID 33303760, 2020).
cancer (93 papers, 1999 to 2026). A tumor composed of atypical neoplastic, often pleomorphic cells that invade other tissues. "Firstly, we explored the relationships between IL2RA expression and cancer-associated pathways and hallmarks in PDAC through GSEA." (PMID 36281157, 2022). "And the finding demonstrated a strong correlation between elevated levels of immune checkpoints and the SREBF1 in ACC, notably KIR2DL3, IL2RA, CD80, IFNG, BTN3A2, and IL1A, also IFNA1 wass significantly associated with SREBF1 in the majority of cancers." (PMID 40668814, 2025). "Recent studies revealed that IL2RA was closely related to the development and progression of tumorigenesis and the prognosis of cancer patients." (PMID 38431660, 2024). "The increased expression level of CCR8, interleukin 2 receptor alpha-chain (IL2RA), and Foxp3 indicate regulatory T cell (Treg) infiltration and contribute to the immunosuppression of T cells against cancer." (PMID 34820403, 2021). "Following, we explored the relationships of IL2RA with anti-cancer immunity responses, abundances of TIICs, and immunotherapy-predicted pathways, demonstrating that high IL2RA expression in PDAC was associated with activated anti-cancer immune activities, TIICs, and immunotherapy responses." (PMID 36281157, 2022). "Super-enhancers have been found in genes involved in T-cell activation (IL2RA/CD25, CD30, and FYN) and known cancer genes (TP73, CCR4, TIAM2, NFATC1, NFATC2, and PIK3R1) in ATL cells." (PMID 38791169, 2024). "Our analysis revealed a positive association between the expression of P2RY6 and immunosuppressive genes such as CD86, CD80, IL2RA, TGFB1, and LGALS9 in pan-cancer." (PMID 37880703, 2023). "We found that this parameter was affected by IL2RA rs7093069 and TNFRSF1B rs2275416, implying the strong impact of genetic variability within immune genes on cancer development, progression, and staging." (PMID 37108754, 2023). "In various types of cancer, findings between NNMT and immunostimulator gene expression showed a high connection (p < 0.05), including TNFSF13B, TNFRSF8, TNFSF14, IL6, IL2RA, CD80, CD27, and CD86." (PMID 36386816, 2022). "Among them, a gradual increase from early-stage cancer to more advanced stages were strongest for APOC2 and IL8 genes followed by for SAA4 and OSM genes, whereas HIST1H1E, PF4V1, CXCL5, and IL2RA expression showed limited stage-wise upregulation." (PMID 33828156, 2021). "Drugs targeting TNFRSF9, IL2RA, FCGR2A, IFNGR2 were found to be potential targets for cancers." (PMID 36857861, 2023). "In addition, five PRIs (HHLA2, IL2RA, TNFRSF18, TNFSF14, and CTLA4) included in the signature were regarded as potential PLAUR-related biomarkers in KIRC, which were studied in other cancers including KIRC based on the current literature." (PMID 36052236, 2022). "While there was no specific inflammation pathway that showed differential methylation, an inflammatory-related gene such as IL2 receptor alpha (IL2RA) included in the pathways in cancer was affected by the differential methylation between non-responders and responders." (PMID 37835379, 2023).
infection (43 papers, 2010 to 2026). The state of being infected such as from the introduction of a foreign agent such as serum, vaccine, antigenic substance or organism. "The IL-2RA+ IL-27− macrophages expressed many heat shock proteins, indicating that these cells were responding to protein-folding induced stress during infection (Data set S1)." (PMID 39882906, 2025). "The Il2 and Csf2 genes were not only the first and third most important genes for the classification of samples regarding the presence of a previous infection but they were also among the genes with the highest correlation with the concentration of different cytokines, together with the Il2ra gene." (PMID 35795182, 2022). "Among these, some became upregulated during the early stage of infection (day 4) CCL7, CXCL11, IL1R1 (cytokine receptor) and IL15RA, and others became upregulated during the late stage of infection (day 7): IL2RA, CSF2RB and others." (PMID 27595844, 2016).
infectious disease (3 papers, 2018 to 2022). A disorder directly resulting from the presence and activity of a microbial, viral, or parasitic agent in humans. "Our results, coupled with Oliveira and colleagues, provide strong evidence of the importance of the IL2RA gene for the severity of infectious diseases caused by intracellular parasites." (PMID 30540075, 2018).
hematological tumors (2 papers, 2021 to 2025). "IL2RA also exhibits prognostic and diagnostic value in hematopoietic cancers and solid cancers." (PMID 34888353, 2021). "In most hematological tumors, FOXP1 expression demonstrated a positive correlation with the expression levels of stimulatory immune genes such as ICOSLG, IL2RA, and HMGB1, and a negative correlation with the expression levels of inhibitory immune genes, such as SLAMF7." (PMID 40672953, 2025).
endocrinopathies (1 paper, 2025). "Other genetic defects that lead to endocrinopathies include loss-of-function changes in IL2RA, STAT5B and GOF in STAT3 and STAT1." (PMID 40704637, 2025).
inflammation (1 paper, 2021). Aberrant reaction of the microcirculation characterized by movement of fluid and leukocytes from the blood into extravascular tissues. "Overall, we identify that duplication of the IL2RA locus can associate with VEO-IBD and suggest that increased IL-2 signaling predisposes to colonic intestinal inflammation." (PMID 34226674, 2021).
IL2RA also shares sentences with these, for which no sentence is quoted: rheumatoid arthritis (20 papers); lymphopenia (14); Hypertension (8); uveitis (8); bacterial infections (7); colorectal cancer (6); depression (6); malaria (6); psoriasis (6); Splenomegaly (6); anemia (5); hemophagocytic syndrome (5); Hemophagocytosis (5); hypertriglyceridemia (5); inflammatory bowel disease (5); Thrombocytopenia (5); B cell lymphoma (4); coagulopathy (4); Granuloma (4); myelofibrosis (4); Stroke (4); fungal infections (3); glioma (3); Hashimoto thyroiditis (3); hematologic malignancies (3); HIV-1 infection (3); Hypofibrinogenemia (3); ischaemic stroke (3); liver inflammation (3); neurosarcoidosis (3).
A further 179 diseases each share a sentence with IL2RA in 3 papers or fewer.